DPP4 (dipeptidyl peptidase 4)
Diseases named in the same sentence as DPP4 in open-access papers (continued):
Sharing a sentence is not in itself a finding about the gene and the disease.
type 2 diabetes (continued). "In response to the addition of a DPP2/4 inhibitor SphK1b expression increased significantly, but not SphK1a, DPP4 is currently used as a drug to manage type II diabetes mellitus and is also associated with inflammatory control." (PMID 36532885, 2022). "An analysis of the National Database of Health Insurance Claims and Specific Health Checkups of Japan reported that, unlike in the United States and Europe, dipeptidyl peptidase-4 (DPP-4) inhibitors are the most frequently prescribed first-line drugs for patients with type 2 diabetes in Japan." (PMID 36078917, 2022). "MEDLINE, Embase, PubMed, Web of Science, and the Cochrane Central Register of Controlled Trials will be used to search for published literature on the pancreatic safety of DPP-4 inhibitors in type 2 diabetes millitus, and clinical trial registries will be used to look for unpublished trials." (PMID 35512071, 2022). "This study will evaluate the pancreatic safety of DPP-4 inhibitors in type 2 diabetes millitus." (PMID 35512071, 2022). "Vice versa, pharmacological activation or inhibition of such enzymes could hold therapeutic potential for a range of diseases including type 2 diabetes, similar to DPP4 inhibitors." (PMID 36343264, 2022). "In this study, we aimed to assess whether use of GLP-1 receptor agonists among patients with type 2 diabetes and stage 5 CKD or ESKD was associated with better outcomes compared with use of DPP-4 inhibitors." (PMID 35254430, 2022). "Since DPP4 inhibition can protect incretin hormones from degradation, DPP4 inhibitors have been widely used in the treatment of type 2 diabetes, and studies have also found that DPP4 plays important roles in cell death regulation, immunity, metabolic regulation, tumorigenesis, and other processes." (PMID 36172198, 2022). "The use of DPP-4 inhibitors can improve glycemic control in patients with type 2 diabetes." (PMID 39280108, 2022). "Included trials will be phase 3 or 4 trials of SGLT2 inhibitors, GLP1 receptor analogues or DPP4 inhibitors, with placebo or active comparators, in participants with type 2 diabetes, with at least one of glycaemic control, change in body weight or major adverse cardiovascular event as outcomes." (PMID 36302574, 2022). "The objective of this study was to determine whether SGLT-2Is vs. dipeptidyl peptidase-4 inhibitors (DPP-4Is) are associated with reductions in MACE, HF hospitalizations and mortality in frail people with type 2 diabetes." (PMID 35903329, 2022). "Incretins reduce glycemic variability (GV) in patients with type 2 diabetes, but it is unknown whether switching from a combination of basal insulin and a DPP-4 inhibitor to insulin degludec/liraglutide (IDegLira) improves GV." (PMID 35097130, 2022). "However, dipeptidyl peptidase-4 (DPP-4) inhibitors are the most commonly prescribed first-line agents for patients with type 2 diabetes in Japan." (PMID 36078917, 2022). "DPP-4 inhibitors have been widely used for the treatment of type II diabetes since 2006." (PMID 34964708, 2022). "This study aimed to compare the efficacies of sodium-glucose cotransporter 2 (SGLT-2) inhibitors, glucagon-like peptide 1 (GLP-1) agonists, and dipeptidyl peptidase 4 (DPP-4) inhibitors on kidney outcomes in patients with type 2 diabetes using network meta-analysis." (PMID 35421174, 2022). "Inhibitors of dipeptidyl peptidase 4 (DPP4i) are commonly used to treat type 2 diabetes." (PMID 34319011, 2021). "Studies have shown that patients treated with DPP4 inhibitor, a commonly used therapy for type 2 diabetes, may accelerate PCa progression following androgen deprivation therapy." (PMID 34556748, 2021). "Sitagliptin is an oral dipeptidyl peptidase 4 (DPP-4) inhibitor, used to treat type II diabetes, and studies have suggested that the SARS-CoV-2 virus may interact with DPP-4 when entering cells." (PMID 34451848, 2021). "In type 2 diabetes, plasma DPP4 activity is increased for glycemic deregulation." (PMID 33514826, 2021).
type 2 diabetes (continued). "We studied in 565 patients with type 2 diabetes in the CovidPredict Clinical Course Cohort whether use of a DPP-4 inhibitor prior to hospital admission due to COVID-19 was associated with improved clinical outcomes." (PMID 34222054, 2021). "Therefore, GLP-1 receptor agonists and DPP-4 inhibitors are effective in the treatment of type 2 diabetes." (PMID 34205264, 2021). "Indeed, several of the type 2 diabetes treatments target β‐cells to induce insulin secretion such as sulfonylureas, dipeptidyl peptidase 4 inhibitors (DPP4i) as well as drugs that act as GLP‐1R and GPR40 agonists." (PMID 34319011, 2021). "Furthermore, DPP-4 inhibitors, such as sitagliptin and vildagliptin, are employed to treat type-2 diabetes as orally effective incretin (both GLP-1 and GIP) enhancers." (PMID 34205659, 2021). "This cohort study compares trends in initiation of treatment with glucagonlike peptide-1 receptor agonists, sodium-glucose cotransporter-2 inhibitors, and dipeptidyl peptidase-4 inhibitors by older adults with type 2 diabetes insured by Medicare Advantage vs commercial health plans." (PMID 33523188, 2021). "Dipeptidyl peptidase (DPP)-4 inhibitor is widely used for type 2 diabetes." (PMID 34063285, 2021). "DPP-4 inhibitors can be used safely for patients with type 2 diabetes with renal impairment." (PMID 34697593, 2021). "The PROLOGUE RCT aimed to investigate whether DPP-4 inhibitors provide cardiovascular protective effects to patients with type 2 diabetes." (PMID 34360051, 2021). "However, no published data are currently available to directly compare glycemic and pleiotropic effects in real-world type 2 diabetes patients initiating SGLT2 inhibitors or DPP4 inhibitors." (PMID 32050968, 2020). "Even in type 2 diabetic patients with end-stage renal disease receiving dialysis, DPP-4 inhibitors could effectively reduce blood glucose and have good renal safety." (PMID 32368255, 2020). "Thus, DPP4 inhibitors have been developed and are clinically available for the treatment of type 2 diabetes." (PMID 31911667, 2020). "DPP4 is a key drug target for the therapy of type II diabetes and diabetic complications." (PMID 32498358, 2020). "A multicenter study compared the GV between DPP4 inhibitor and glimepiride groups, and found that DPP4 inhibitors were more effective than glimepiride in reducing GV as initial combination therapy with metformin in patients with type 2 diabetes." (PMID 32622354, 2020). "In addition to treating type 2 diabetes, DPP4 is reported to improve the function of endothelial cells." (PMID 32714856, 2020). "Moreover, as dipeptidyl peptidase-4 (DPP-4) inhibitors have emerged as a useful tool in treating type 2 diabetes, our previous reports showed that DPP-4 activity is crucial to the downstream insulin resistance signals." (PMID 33267804, 2020). "Because of this reduction in cardiovascular event risk by lowering SBP, our findings suggest that compared to DPP4 inhibitors, SGLT2 inhibitors as intensification therapy may provide a more valuable therapeutic option in type 2 diabetes patients." (PMID 32050968, 2020). "However, 11 of the stroke participants had known type 2 diabetes and were currently being treated (seven on metformin, glyburide or both; three on some form of insulin injection; one on a DPP4 inhibitor)." (PMID 33375333, 2020). "Observational data from two recent trials of inhibitors of dipeptidyl-peptidase 4 have revealed U-shaped relationships between SBP and adjusted CVD rates in patients with type 2 diabetes and established cardiovascular disease or multiple risk factors but did not evaluate the risk of death." (PMID 33046070, 2020). "However, little clinical evidence for DPP4 activity in newly diagnosed type 2 diabetes is available." (PMID 33312197, 2020). "Sitagliptin is a type 2 diabetes treatment drug, which acts by inhibiting the activity of DPP4." (PMID 32774687, 2020).
type 2 diabetes (continued). "In this study, we have demonstrated, for the first time, that the SGLT2 inhibitor empagliflozin, the DPP4 inhibitor linagliptin, and a combination of these agents, could reactivate glomerular autophagy in db/db mice, a model of type 2 diabetes." (PMID 32340263, 2020). "The importance of DPP4 for the scientific and medical community has considerably raised since the approval of inhibitors of DPP4 activity, known as gliptins, for the treatment of type 2 diabetes (T2D)." (PMID 33329052, 2020). "Dipeptidyl peptidase-4 (DPP-4) inhibitors have been approved for the treatment of type 2 diabetes." (PMID 32937958, 2020). "Similarly, dipeptidyl peptidase 4 (DPP-4), a well-known target in type II diabetes mellitus, has differential effects on cancer types." (PMID 32498358, 2020). "In addition, patients included in the previous randomized controlled trial using SGLT2 inhibitors and DPP-4 inhibitors had high prevalence of cardiovascular disease with long duration of type 2 diabetes." (PMID 31910850, 2020). "The first DPP-4 inhibitor which was used in a clinical study in type 2 diabetes was NVP DPP728." (PMID 31275243, 2019). "This phase in the path to clinical use of DPP-4 inhibitors was followed with a rapid development during the 2000s with clinical studies of several different DPP-4 inhibitors which ended in 2006–2013 with their approval for use in subjects with type 2 diabetes." (PMID 31275243, 2019). "Therefore, more stable exendin-based GLP-1, GLP-1 human analogues, and DPP-4 inhibitors have been developed as therapeutic drugs for the treatment of type 2 diabetes." (PMID 31336911, 2019). "In these phase III studies the DPP-4 inhibitors were examined as monotherapy in drug-naïve patients and as add-on to on-going therapy with metformin, sulfonylurea therapy, thiazolidinedione therapy and therapy with exogenous insulin in type 2 diabetes." (PMID 31275243, 2019). "Similarly, teneligliptin, a dipeptidyl peptidase-4 (DPP-4) inhibitor, significantly reduced plasma levels of platelet-shed MPs and plasminogen activator inhibitor in type-2 diabetes patients receiving hemodialysis." (PMID 30915196, 2019). "DPP-4 inhibitors were introduced for the treatment of type 2 diabetes in 2006." (PMID 31275246, 2019). "Dipeptidyl peptidase-4 (DPP-4) inhibitors are novel anti-hyperglycemic drugs for type 2 diabetes." (PMID 30858802, 2019). "Oral DPP4 inhibitors (gliptins) are used in type-2 diabetes to potentiate GLP-1 signaling." (PMID 31956307, 2019). "Further studies in which the relationship between effects of DPP-4 inhibitors on SDF-1α levels is evaluated in a murine model of type 2 diabetes may reveal the reason for this discrepancy." (PMID 31308448, 2019). "Kishimoto M. Teneligliptin: a DPP-4 inhibitor for the treatment of type 2 diabetes." (PMID 29527102, 2018). "However, to the best of our knowledge, the present meta-analysis is the first to evaluate the efficacy and safety of the combination of an SGLT2 inhibitor and a DPP4 inhibitor in patients with inadequately controlled type 2 diabetes." (PMID 29535389, 2018). "In human randomized, double-blind clinical studies, DPP-4 inhibitors did not appear to reduce the risk of major adverse cardiovascular events among patients with type 2 diabetes without and with established cardiovascular disease." (PMID 29308090, 2018). "On the basis of these and other studies, it appears that there is a cross-talk between AGE-RAGE signaling and the DPP-4/incretin system, which may represent a novel therapeutic target for preventing vascular complications of type 2 diabetes." (PMID 29491123, 2018). "The same was true for teneligliptin, a novel DPP4 inhibitor, that was found to ameliorate endothelial function and to reduce renal and vascular oxidative stress in patients with type 2 diabetes and chronic kidney disease, irrespectively of reducing albuminuria or glycaemia." (PMID 29310645, 2018).
type 2 diabetes (continued). "Emerging evidence suggests that dipeptidyl peptidase-4 (DPP-4) inhibitors used to treat type 2 diabetes may have nephroprotective effects beyond the reduced renal risk conferred by glycemic control." (PMID 29491123, 2018). "In conclusion, the SGLT2 inhibitor and DPP4 inhibitor combination therapy improves glycemic control and reduces body weight without increasing the risk of hypoglycemia and UTI in patients with inadequately controlled type 2 diabetes." (PMID 29535389, 2018). "Dipeptidyl peptidase-4 (DPP-4) is a target to treat type II diabetes mellitus." (PMID 29473857, 2018). "Dipeptidyl peptidase-4 (DPP-4) inhibitors, such as alogliptin, which increases incretin levels to inhibit glucagon release leading to increased insulin secretion are also a common treatment for type 2 diabetes." (PMID 30534081, 2018). "Therefore, we performed a systematic review and meta-analysis to assess the efficacy and safety of a combination of an SGLT2 inhibitor and a DPP4 inhibitor in patients with suboptimally controlled type 2 diabetes." (PMID 29535389, 2018). "Dipeptidyl peptidase-4 inhibitors in the treatment of type 2 diabetes: a comparative review." (PMID 29527102, 2018). "Sitagliptin increased DPP4 expression in skeletal muscle, which seems counterintuitive since high local DPP4 levels are thought to impair insulin signalling and thereby induce/deteriorate the development of type 2 diabetes." (PMID 30145664, 2018). "Sitagliptin is a selective dipeptidyl peptidase-4 inhibitor for the treatment of patients with type 2 diabetes and is sometimes used in combination with other classes of antidiabetic agents such as glinides (e.g., mitiglinide and repaglinide) and α-glycosidase inhibitors (e.g., miglitol)." (PMID 30452488, 2018). "The results of a 12-week clinical trial of teneligliptin revealed that at week 12 the mean percentage inhibition of plasma DPP-4 activity (measured pre-dose) following teneligliptin 20 and 40 mg once daily was 61.1% and 73.3%, respectively, in Japanese patients with type 2 diabetes." (PMID 29435909, 2018). "DPP-4 inhibitors entered clinical practice as approved therapeutics for type-2 diabetes in 2006." (PMID 28750074, 2017). "Dipeptidyl peptidase-4 inhibitors are widely used in type 2 diabetes." (PMID 27530507, 2017). "Thus, we have identified, designed and synthesized a novel dual-target compound, HBK001, which represents a promising therapeutic candidate for type 2 diabetes, especially for patients who are insensitive to current DPP4 inhibitors." (PMID 28659588, 2017). "DPP-4 inhibitors are now widely used for the treatment of type 2 diabetes." (PMID 28761658, 2017). "Furthermore, previous articles showed that the short-term and long-term glucose-lowering effects by DPP-4 inhibitor were less in obese people with type 2 diabetes." (PMID 28626771, 2017). "If corroborated in respective pharmacogenetic studies, this gene variation could influence clinical decisions, e.g., regarding the use of DPP-4 inhibitors versus incretin mimetics, in terms of individualized therapy of type-2 diabetes." (PMID 28750074, 2017). "A decreased risk of hospitalization for CVDs was found among patients with a history of visit for CVDs (aHR, 0.73; 95% CI, 0.56–0.97) or with >2.5 years’ duration of type 2 diabetes (aHR, 0.77; 95% CI, 0.66–0.91) in the DPP-4 inhibitors versus glimepiride group." (PMID 28640111, 2017). "The mechanism by which the DPP-4 inhibitor could influence the lipid profile in patients with type 2 diabetes has not been fully understood." (PMID 28403877, 2017). "Either a DPP-4 inhibitor or an SGLT2 inhibitor may be beneficial in patients with type 2 diabetes for CVD." (PMID 28403877, 2017). "Dipeptidyl peptidase-4 (DPP-4) inhibitors may have protective effects in the early stage of atherosclerosis in patients with type 2 diabetes, although similar effects in advanced atherosclerosis were not shown in recent randomized placebo-controlled studies." (PMID 29017497, 2017).
type 2 diabetes (continued). "In general, studies of DPP-4 inhibitors have shown similar or better safety than placebo and other antidiabetic drugs in older adults with type 2 diabetes, but these safety data are mainly based on short-term outcomes like hypoglycaemic events and acute adverse events." (PMID 29047372, 2017). "However, previous studies have shown that the effects of DPP-4 inhibitors on HbA1c in patients with type 2 diabetes are highest in the first year, and then begin to decline from the second year of treatment." (PMID 28182722, 2017). "Therefore, in order to maintain glucose-lowering effect by DPP-4 inhibitor for a long time, it is necessary to keep strict triglyceride management especially in obese subjects with type 2 diabetes." (PMID 28626771, 2017). "But multivariate regression analysis, which included both body weight change and average triglyceride as independent variables, demonstrated that average triglyceride was an independent factor determining the durability of DPP-4 inhibitor in subjects with type 2 diabetes." (PMID 28626771, 2017). "The study subjects were new users of DPP-4 inhibitors or glimepiride for type 2 diabetes." (PMID 28640111, 2017). "Our study suggests that emodin inhibits DPP4 activity and may represent a novel therapeutic for the treatment of type 2 diabetes." (PMID 28507818, 2017). "We assessed the effects of DPP-4 inhibitors on the homoeostasis model assessment beta-cell function (HOMA-B) or insulin resistance (HOMA-IR) index in patients with type 2 diabetes through a systematic review and meta-analysis of randomized controlled trials (RCTs)." (PMID 28322294, 2017). "On the other hand, the mechanism of DPP-4 inhibitors, such as sitagliptin, on the protective effect of renal function in type 2 diabetes patients complicated with hypertension remains unclear." (PMID 29340105, 2017). "Like incretins, DPP-4 inhibitors also elicit beneficial effects against DR, with oral administration of sitagliptin preventing the pathological changes in the blood-retinal barrier in a rat model of type 2 diabetes." (PMID 26881236, 2016). "However, this is the first report to show that a DPP-4 inhibitor exerts a dose-dependent, organ-specific effect on the macro- and microvascular complications in type 2 diabetes model." (PMID 26959365, 2016). "Therefore, we carried out the present study as a sub-analysis of the PROLOGUE study to evaluate the long-term effect of a DPP-4 inhibitor on endothelial function assessed by FMD in the brachial artery in patients with type 2 diabetes." (PMID 27624168, 2016). "It is also half of the cost of anti-hypertensive drugs for the prevention of cardiovascular events and nearly 3 times less than the cost of DPP-4 inhibitors for the treatment of diabetes type 2 or the cost of antithrombotic drugs for the prevention of recurrent stroke." (PMID 27050111, 2016). "In summary, the current analysis suggested that the use of DPP-4 inhibitor does not decrease the risk of fracture in patients with type 2 diabetes." (PMID 27384445, 2016). "Dipeptidyl peptidase 4 (DPP4) inhibitors improve glycemic control in type 2 diabetes, however, their influence on the retinal neurovascular unit remains unclear." (PMID 27942008, 2016). "Saxagliptin (rINN), previously identified as BMS-477118, linagliptin (BI-1356), vildagliptin (LAF237), sitagliptin (MK-0431), and alogliptin are oral hypoglycemic agent of the dipeptidyl peptidase-4 (DPP-4) inhibitor class of drugs approved by the FDA for management of type 2 diabetes in adults." (PMID 27413253, 2016). "The study showed that DPP-4 inhibitor use does not modify the risk of bone fracture compared with placebo or other anti-diabetic medications in patients with type 2 diabetes." (PMID 27384445, 2016). "Dipeptidyl peptidase-4 (DPP-4) inhibitors have been shown to reduce hemoglobin A1c (HbA1c) in patients with type 2 diabetes, but the reduction varies between patients and adequate glycemic control may not be achieved." (PMID 26767082, 2016).